VCP (valosin containing protein)
Diseases named in the same sentence as VCP in open-access papers (continued):
Sharing a sentence is not in itself a finding about the gene and the disease.
cancer (continued). "Previous studies showed an augmented expression of p97/VCP in different types of human cancer cells." (PMID 39473740, 2024). "UPR activation has also been observed in various cancer types upon genetic suppression or pharmacologic inhibition of VCP." (PMID 36923647, 2023). "Recently, some studies have revealed that VCP is a potential target for cancer therapy including MM, and confirmed the significant biological effects of small molecule inhibitors against VCP." (PMID 37606987, 2023). "The discovery of molecules that inhibit P97/VCP is an important step in the treatment of cancer in humans." (PMID 37374283, 2023). "Studies have shown that there is a relationship between increased p97/VCP expression and cancer prognosis and metastatic potential." (PMID 37374283, 2023). "Elevated VCP expression has been observed in multiple cancer types, including PDAC, and correlates with worse patient survival." (PMID 36923647, 2023). "Mechanistic links between VCP and cell death are underscored by VCP inhibitors that trigger cancer cell death." (PMID 37545006, 2023). "In the future, it is necessary to find new treatments for cancer and other diseases by developing inhibitors such as those targeting VCP." (PMID 37269429, 2023). "While VCP has been heavily studied in the context of other cancer types, the mechanisms of VCP that modulate KRAS-mutant PDAC growth remain less well understood." (PMID 36923647, 2023). "Clinical studies have correlated VCP overexpression to advanced disease, metastasis, and worse patient outcome in many cancers including PDAC." (PMID 36923647, 2023). "This peptide pool contained proteins involved in cancer development and migration, such as Fascin, Ape-1, Bcl-2, and VCP." (PMID 36679991, 2023). "This is the first study that expands the phenotype of VCP disease to potentially include rare cancers and highlights the importance of further investigation of the role of VCP in cancer development." (PMID 35841038, 2022). "HBx is able to promote NF-κB activation through regulating ECSIT, VHL-binding protein (VBP1), amplification in breast cancer 1 (AIB1) or valosin-containing protein (VCP)." (PMID 36298831, 2022). "Since VCP inhibitors display cytotoxicity towards multiple cancer types, the combination of VCP inhibitors and mifepristone should show efficacy in other cancer types." (PMID 35740614, 2022). "It has been well-documented that VCP is overexpressed in multiple types of cancers and has been suggested as a marker for prognosis." (PMID 35841038, 2022). "Increased VCP expression is related to more aggressive cancer types and reduced iodide uptake, and VCP was suggested as a prognostic biomarker for FTC36,37." (PMID 35136135, 2022). "Taken together, these data suggest that VCP is involved in the progression of several cancer types including HCC via multiple mechanisms." (PMID 35562734, 2022). "The study reported enhanced biochemical inhibition towards VCP, increased in vitro cytotoxicity in several cancer types, as well as pronounced in vivo efficacy in multiple mouse tumor xenograft models with CB-5083." (PMID 35740614, 2022). "Recently, valosin-containing protein has emerged as a key component of the pathway and a novel therapeutic target for cancer treatment." (PMID 35740614, 2022). "Based on the evidence for a strong relationship between cancer and VCP function, and up-regulation of VCP activity caused by IBMPFD-related VCP variants, we conducted this study to characterize cancers in this group of patients." (PMID 35841038, 2022). "It has been demonstrated that the expression level of VCP is significantly elevated in several different types of cancer, including non-small cell lung carcinomas, pancreatic endocrine neoplasms, and prostate cancer." (PMID 35841038, 2022). "VCP/p97 functions in several hallmarks of cancer have been largely reported and specific inhibitors have been developed and tested for cancer treatment." (PMID 35158912, 2022).
cancer (continued). "p97/VCP overexpresses in many cancers due to its essential role in protein homeostasis and protein quality control, and is a promising anticancer target." (PMID 35456598, 2022). "A potential topic of future research would be to further study the molecular mechanisms implicating VCP in human cancer cells." (PMID 35841038, 2022). "A previous study on rodent cancer xenograft models with elevated VCP expression showed that CB-5083 can significantly decrease tumor progression and growth." (PMID 34998409, 2022). "Recent evidence supports the concept that VCP acts as a regulator of cellular metabolism through its link to multiple metabolic processes in cancer cell lines and in patient-derived multiple myeloma cells." (PMID 35841038, 2022). "Increased VCP protein expression is observed in many cancers and correlates with poor patient outcomes." (PMID 36196920, 2022). "NMS-873 is an allosteric p97/VCP inhibitor, which is known to activate the unfolded protein response, interfere with autophagy, and to induce cancer cell death through apoptosis." (PMID 36288698, 2022). "The human AAA+ ATPase p97, also known as valosin-containing protein, a potential target for cancer therapeutics, plays a vital role in the clearing of misfolded proteins." (PMID 34520757, 2021). "This study supports that VCP is a pan-flaviviral host dependency factor and constitutes an attractive antiviral target, especially considering that new generation VCP drugs are currently evaluated in clinical trials for cancer treatment." (PMID 34696522, 2021). "Recently, a novel VCP/p97-mediated survival mechanism based on the metabolic adaptation of cancer cells to starvation through the inhibition of mitochondrial activity was identified in the prostate cancer cell line PC3." (PMID 34576340, 2021). "In patients with locally advanced ESCC who were treated with radiotherapy, VCP/p97 expression was significantly increased in the cytoplasm of cancer cells when assessed using immunohistochemistry, and its elevated expression indicated shorter overall survival." (PMID 34576340, 2021). "They found that a small-molecule ligand (NPD8733) of valosin-containing protein/p97 inhibited cancer cell–accelerated fibroblast migration." (PMID 33968752, 2021). "Since VCP has important molecular and cellular roles and is involved in diverse physiological and pathological conditions, such as cancer, it is an interesting and potential therapeutic target." (PMID 34576340, 2021). "Given the ubiquitously important role of VCP in DNA damage response across various tissue types, our findings likely have far-reaching relevance for other cancer types in addition to PDAC." (PMID 34680224, 2021). "Altered VCP/p97 expression has been identified in different cancer types and correlates with patient outcomes, as it is functionally associated with aggressiveness and therapeutic resistance." (PMID 34576340, 2021). "It was also reported that p97/VCP levels are generally higher in serums obtained from cancer patients compared to healthy individuals." (PMID 32002125, 2020). "It has been shown that the inhibition of VCP is able to induce proteotoxic stress and apoptosis in cancer cells, and improve radiation sensitivity in ESCC." (PMID 32481679, 2020). "Consistently, our model suggests that in cancer cells where p97/VCP is more abundant, RhoA level turnover is misregulated." (PMID 32002125, 2020). "Evidence also indicates that VCP plays an important role in the metastatic process in cancer cells, by involvement in the ubiquitin-dependent proteasome degradation pathway via the Akt/NFκB pathway." (PMID 32481679, 2020). "Several studies have revealed the potential mechanisms of VCP involved in cancer cell reprogramming." (PMID 32481679, 2020). "VCP is a ubiquitous ATPase that is elevated in several tumors, and its inhibition promotes cancer cell death via autophagy." (PMID 33488754, 2020).
cancer (continued). "It is also necessary to explore the mechanisms that stimulate VCP in cancer cells, or their reduction under cardiac stress, which will lead to the discovery of the pathogenesis of the related diseases." (PMID 32481679, 2020). "In this review, we have summarized the involvement of VCP in a variety of pathological conditions, particularly in cancers, neurodegenerative disorders and heart diseases." (PMID 32481679, 2020). "In this review, we summarized the new progress achieved in studies of VCP, regarding its regulating effect on ER and mitochondria functions, and its implications for various diseases, focusing on cancer, heart disease and neurodegenerative disorders." (PMID 32481679, 2020). "This led to an interest in the inhibition of VCP, a common essential protein in cancer, since such inhibition would result in increased proteotoxic stress and subsequent cell death in cancer." (PMID 31358864, 2019). "P97/VCP is considered to be upregulated in multiple diseases and cancers, this highlights its importance as a potential therapeutic target." (PMID 31671908, 2019). "In summary, we uncovered a role for VCP/p97 in cancer cell metabolism and in maintaining cancer cell ER protein homoeostasis under nutrient-restricted conditions." (PMID 30626938, 2019). "NMS-873, an allosteric inhibitor of P97/VCP, was shown to interfere with protein degradation and to induce cancer cell death." (PMID 31671908, 2019). "Recently, an important role of VCP in maintaining cancer cell homeostasis in conditions of nutrient (glutamine) depletion was reported." (PMID 31456945, 2019). "We found that VCP/p97 mRNA expression across 917 CCLE cancer cell lines significantly correlated with 162 Kyoto Encyclopedia of Genes and Genomes (KEGG) terms." (PMID 30626938, 2019). "Prompted by the potential application of VCP inhibitors in cancer, several studies have focused on understanding the mechanism of resistance towards VCP inhibitors." (PMID 29367883, 2017). "VCP has emerged as a viable therapeutic target for several cancer types, and therefore targeting such hyperactive VCP mutants should aid in improving the therapeutic outcome in cancer patients." (PMID 29367883, 2017). "VCP has been identified as a potential anti-cancer target and as such a number of small molecule inhibitors have been developed, the most potent of which is NMS-873." (PMID 28494016, 2017). "Because VCP is a potential anti-cancer target, a number of effective small molecule inhibitors of VCP have been developed." (PMID 28494016, 2017). "VCP has also been shown to inhibit IκB, which is the endogenous inhibitor of NFκB, a transcription factor that promotes cellular (cancer cell) proliferation and inhibits apoptosis." (PMID 27434122, 2016). "Valosin-containing protein (VCP or p97) is a promising molecular target for anti-cancer drug therapeutics." (PMID 27434122, 2016). "This is achieved by a significantly higher expression of VCP in a myriad variety of cancer cells, including NSCLC." (PMID 27434122, 2016). "We have reported the in vitro and in vivo anti-cancer potential of inhibiting VCP expression or function using si/sh-RNA or small-molecule drugs such as Eeyarestatin I (EerI) in our earlier study." (PMID 27434122, 2016). "We show that Jurkat tumoral cells, and also other leukemic human cells, such as U937 and Mec1, are more sensitive to cell death induced by the VCP inhibitor DBeQ than normal human T cells, suggesting a new selective pathway to exploit in cancer treatment." (PMID 27086912, 2016). "Although distributed in normal cells and needed for many physiological cell processes, p97/VCP ubiquitin is overexpressed in malignant cells in many different types of cancer." (PMID 26934314, 2016). "Our lab and others have previously shown that cancerous cells have increased levels of VCP, which allows the cancer cells to proliferate and metastasize." (PMID 27434122, 2016).
cancer (continued). "Overexpression of VCP occurs in many cancers, and often in a manner correlating with malignancy and poor outcome." (PMID 26104798, 2015). "The data suggest that the effects of VCP inhibitors have different mechanisms of action from proteasome inhibitors, and that their effects are not limited to cancer cells with a distinctive secretory load, such as MM cells." (PMID 26720340, 2015). "Evidence is accumulating that suggests that VCP represents a valid therapeutic target for a range of cancers." (PMID 26104798, 2015). "The ATPase valosin-containing protein (VCP; p97) is an essential regulator of protein degradation in multiple pathways and has emerged as a target for cancer therapy." (PMID 26720340, 2015). "Valosin-containing protein (VCP, also known as p97) has been shown to be associated with metastatic potential of cancer cells using the mRNA subtraction technique." (PMID 25463965, 2014). "VCP is also active in the ubiquitin/proteasome-degradation pathway, which is involved in proliferation and anti-apoptosis in human cancer cells." (PMID 25009651, 2014). "Significantly, VCP has been shown to promote tumor suppressor protein 53BP1 recruitment to DNA damage sites to repair the damage, providing defense against cancer for normal cells." (PMID 23755301, 2013). "Role of VCP/Cdc48 in fluctuating number of death cell in various types of disease naming cancer and protein deposition diseases is not well understood." (PMID 23233838, 2012). "Taken together, our results indicate that VCP represents a highly sensitive, potentially clinically useful serum tumor marker for a variety of human cancers." (PMID 22870330, 2012). "Among these proteins, only VCP was present in significantly increased levels in the preoperative serum of GCT cancer patients compared to normal subjects." (PMID 22870330, 2012). "Increase in expression of VCP is correlated to the development of cancer and metastasis therefore detecting the level of VCP expression is proposed as cancer progression marker." (PMID 23233838, 2012). "High level of VCP expression in cancer cells has been shown to correlate with the increase in recurrence rate and poor prognosis of patients with cancer of the liver, stomach, prostate and esophagus." (PMID 20543960, 2010). "Notably, the expression profile of various RQC factors (e.g., ASCC3, ABCE1, ANKZF1, and VCP) is dysregulated in cancer." (PMID 38798583, 2026). "This study quantified and validated four cervical precancer and cancer biomarkers—TOP2A, MCM2, VCP, and p16INK4a—in lysates of cultured HeLa, Ca Ski, HT-3, and C-33 A cancer cell lines, as well as normal PCS cells, clinical cervical swab specimens, and cervical tissues." (PMID 40507244, 2025). "Finally, analysis of hub proteins, such as VCP, revealed their central role in cancer PPI networks and potential as drug targets." (PMID 40732248, 2025). "The inhibition of ABCE1, ASCC3, and VCP has been shown to impede cancer cell proliferation and viability, while inhibiting NEMF/Clbn and ZNF598 may facilitate cancer cell growth and survival." (PMID 40785597, 2025). "VCP and p16INK4a were overexpressed across all cancer cell lines compared to primary cells." (PMID 40507244, 2025). "Additionally, our findings demonstrated that mTORC2 activation is essential for the selective action of VCP inhibitors in cancer cells." (PMID 38218922, 2024). "The susceptibility of cancer cells to VCP inhibition is attributed to the non-attenuation and recovery of protein synthesis under proteotoxic stress." (PMID 38218922, 2024). "Finally, ASPSCR1::TFE3 and VCP demonstrate co-dependence for cancer cell proliferation and tumorigenesis in vitro and in ASPS and RCC mouse models, underscoring VCP’s potential as a novel therapeutic target." (PMID 38326311, 2024). "In summary, our work suggests that inducing paraptosis through VCP inhibition may open up novel therapeutic avenues for cancer cells characterized by hyperactive Akt." (PMID 38218922, 2024).
cancer (continued). "Interestingly, a similar activation of the UPR by VCP inhibition was observed in additional cancer cell lines, such as Jurkat and K562 cells, indicating a conserved mechanism across various cancer types." (PMID 38727283, 2024). "Additionally, inhibiting KRT80 can partially counter the cancer-promoting effects of VCP in LUAD and its downstream pathway PI3K." (PMID 38495507, 2024). "Multiple efforts have attempted unsuccessfully to target VCP with small molecules to treat cancer." (PMID 38826306, 2024). "We investigated whether mTOR signaling plays a similar role in cancer cells undergoing VCP inhibition-induced paraptosis." (PMID 38218922, 2024). "The VCP adaptor Npl4 has been used as a potential anti-cancer target in vitro." (PMID 38891822, 2024). "Notably, VCP is frequently overexpressed in various cancer types and holds promise as both a cancer prognostic biomarker and therapeutic target." (PMID 38218922, 2024). "In addition, significant changes in p97/VCP expression have been observed in many cancer types, and the use of proteasome inhibitors, such as bortezomib, or p97/VCP inhibitors, such as DBeQ, has been suggested in the treatment of cancer or cancerous tissue." (PMID 39473740, 2024). "Interfering with KRT80 expression can influence the cancer-promoting effects driven by VCP." (PMID 38495507, 2024). "The targeting of VCP activity has therefore emerged as a promising therapeutic option in cancer." (PMID 37631252, 2023). "VCP inhibitors have gradually shown great potential for cancer treatment." (PMID 37606987, 2023). "Online database analysis showed that VCP was highly expressed in most cancer tissues." (PMID 37269429, 2023). "Adverse effects may be tolerable if systemic VCP inhibition occurs over a limited period of time, for example to boost the elimination of cancer cells." (PMID 37545006, 2023). "It is a promising strategy to develop small-molecule inhibitors of VCP for cancer treatment." (PMID 37606987, 2023). "Additionally, since oral VCP inhibitors display a pan-cancer cytotoxicity, our results have broad implications in terms of designing future combination clinical trials with VCP inhibitors." (PMID 35740614, 2022). "VCP maintains cancer cell metabolic and protein homoeostasis through its correlation with GCN2 (general control nonderepressible 2), a serine/threonine-protein amino acid-sensing kinase, that plays a key role in modulating amino acid metabolism as a response to nutrient deprivation." (PMID 35841038, 2022). "Expression of VCP in cancers has been correlated with tumor aggressiveness and prognosis." (PMID 35841038, 2022). "Although active cancer screening for patients with germline VCP variants is not recommended, if those patients develop cancer, they need to be followed up closely for signs of local invasion or metastasis." (PMID 35841038, 2022). "Targeting VCP as a potential cancer treatment has been an effective method in multiple studies." (PMID 35841038, 2022). "Multiple ATP-competitive, covalent, and allosteric VCP inhibitors have been developed as anti-cancer compounds and may be re-purposed or further developed as anti-virals." (PMID 36196920, 2022). "Since VCP inhibitors display cytotoxicity towards multiple different cancer types, the combination of VCP inhibitors and mifepristone may show efficacy in other cancer types." (PMID 35740614, 2022). "The expression of VCP was first evaluated using public cancer databases." (PMID 35562734, 2022). "Although its exact role in cancer activity remains unknown, it has been shown that VCP inhibitors can result in cancer cell death, suggesting the possible use of VCP inhibition as a potential cancer therapy." (PMID 35841038, 2022). "Functional studies have shown that inhibition of ABCE1, ASCC3, and VCP may inhibit cancer cell growth and survival, whereas inhibition of NEMF/Clbn and ZNF598 may have opposite effects." (PMID 36187485, 2022).